ZNF772 (zinc finger protein 772)
Description:
May be involved in transcriptional regulation.
Synonyms: DKFZp686I1569
Tractability: PROTAC: ubiquitination databases record sites on it.
Gene: Protein-coding gene on chromosome 19 (57,466,663 to 57,477,570, reverse strand). Ensembl gene ENSG00000197128.
Subcellular location: Nucleus
Subcellular location (Human Protein Atlas): Cytosol
Pathways (Reactome):
Gene expression (Transcription): Generic Transcription Pathway
Gene Ontology:
Molecular function: protein binding; DNA-binding transcription factor activity, RNA polymerase II-specific; RNA polymerase II cis-regulatory region sequence-specific DNA binding
Biological process: regulation of transcription by RNA polymerase II; regulation of DNA-templated transcription
Cellular component: nucleus
Genetic constraint (gnomAD): Loss-of-function variants: 8 observed, 12.88 expected, observed/expected ratio (o/e) 0.62, 90% interval 0.36 to 1.12. The upper end of that interval is the gene's LOEUF score, 1.12, which puts it in group 4 of 6, group 1 being the genes least tolerant of losing a copy. Missense variants: 496 observed, 580.79 expected, observed/expected ratio (o/e) 0.85, 90% interval 0.79 to 0.92. Synonymous variants: 155 observed, 190.35 expected, observed/expected ratio (o/e) 0.81, 90% interval 0.71 to 0.93.
Homologues: Orthologues: dog ZNF772 (83% identical), pig ZNF772 (70% identical), rat Zfy1 (21% identical), mouse Zfy1 (21% identical), mouse Zfy2 (21% identical), tropical clawed frog zfx (21% identical), zebrafish zfx (20% identical). Paralogues in human: ZNF304 (59% identical), ZNF256 (56% identical), ZNF134 (53% identical), ZNF551 (53% identical), ZNF792 (52% identical), ZNF549 (51% identical), ZNF548 (51% identical), ZNF587B (51% identical), ZNF418 (46% identical), ZNF154 (45% identical), ZNF773 (44% identical), ZNF419 (44% identical), and 26 more.
Diseases named in the same sentence as ZNF772 in open-access papers:
ZNF772 is named in the same sentence as 1 disease in open-access papers, as found by Europe PMC text mining. Sharing a sentence is not in itself a finding about the gene and the disease.
ZNF772 shares sentences with these, for which no sentence is quoted: hypopharyngeal carcinoma (1 paper).